AR (androgen receptor)
Diseases named in the same sentence as AR in open-access papers (continued):
Sharing a sentence is not in itself a finding about the gene and the disease.
acne (continued). "In this manner, the findings of our study support the notion that FGFR signalling and AR signalling form a cyclization to drive the formation of acne lesions." (PMID 36803994, 2023). "In skin tissues suffering from acne, AR signalling triggers the transcription of two FGFR2 ligands, FGF-7 (also known as keratinocyte growth factor, KGF) and FGF-10, which results in the activation of FGFR2 signalling." (PMID 36803994, 2023). "In the areas of the skin where acne lesions appear, there is a greater expression of the androgen receptor and the enzyme 5α reductase, which converts T into DHT, which is the most potent androgen." (PMID 35889022, 2022). "The topical androgen receptor inhibitor clascoterone is a novel promising therapeutic option for acne." (PMID 35806952, 2022). "The occurrence of acne, a chronic inflammatory disease, is likely to be reduced if the inflammatory response can be suppressed 5α-R1 activates DHT, which binds to the androgen receptor and causes acne." (PMID 36624865, 2022). "Spironolactone, an AR antagonist, is also sometimes used off-label and is effective in adult female patients with acne and adolescents with PCOS." (PMID 34207527, 2021). "At puberty onset, upregulation of AR signalling is likely to explain the downregulation of GATA6 we observe in acne samples." (PMID 33082341, 2020). "Both of these AR blockers are observed to be effective in significantly decreasing levels of hirsutism and acne in PCOS patients." (PMID 31466345, 2019). "Increased IGF-1 signalling in acne suppresses nuclear FoxO1, which is a nuclear co-suppressor of AR, and thus increases AR-mediated target gene expression." (PMID 28927457, 2017). "It is important to note that nuclear FoxO1, the transcription factor of starvation, suppresses the androgen receptor (AR), a critical acne-inducing pathway also involved in PCa." (PMID 28814964, 2017). "Specifically, ASC-J9, a curcumin derivative that is in clinical trial for acne treatment, has been reported to possess AR-degradation–enhancing activity." (PMID 24742982, 2014). "Therefore, in clinical practice, for patients experiencing acne and hirsutism, local treatments or the use of spironolactone to block the androgen receptor activity can be considered." (PMID 40773444, 2025). "Among several pathologies of acne lesions, amplification of AR signalling is vital." (PMID 36803994, 2023). "Even so, acne does not develop when there is loss of functionality of the androgen receptor, but IGF-1 is the main hormone that controls pubertal development, and decreases after this phase." (PMID 35889022, 2022). "Genetic studies have shown that dysregulation of the AR occurs in people experiencing severe acne." (PMID 34207527, 2021). "This suggests that there may be gender differences in the association between AR CAG repeat VNTR and both acne and acne severity." (PMID 33849530, 2021).
acne (continued). "Moreover, milk and dairy products act as enhancers of insulin/IGF-1 signalling, supporting sebaceous lipogenesis and acne aggravation through the derepression of the androgen receptor." (PMID 25977937, 2015). "Moreover, IGF-1 is able to stimulate 5α reductase, adrenal and gonadal androgen synthesis, androgen receptor signal transduction, sebocyte proliferation, sebum production, and lipogenesis, affecting acne development." (PMID 25977937, 2015). "Notably, androgen-insensitive subjects who lack functional ARs do not produce sebum and do not develop acne, underlining the important contribution of AR signaling in the pathogenesis of acne." (PMID 37998335, 2023). "Interestingly, hormonal treatment of acne in female patients may involve spironolactone, a drug that suppresses androgen receptor signaling." (PMID 34207527, 2021). "Notably, EDCs are known to selectively enhance AR and PPARy-mediated expression of lipogenic genes and subsequent lipogenesis, providing a plausible link between EDCs exposure and enhanced sebaceous gland activity in acne." (PMID 34207527, 2021). "Furthermore, in vitro results suggest that acne patients carrying fewer CAG repeats may exhibit a higher AR mRNA and protein expression, leading to higher sensitivity to androgens than in control individuals." (PMID 33849530, 2021). "IGF-1 signaling, critical in acne development, regulates the PI3K/Akt cascade and FoxO1 activity, impacting lipogenesis and androgen receptor (AR) transactivation and influencing lipid synthesis and sebaceous secretion." (PMID 38791344, 2024). "Overall, we demonstrate that a polysaccharide-conjugated and naturally derived oligopeptide HA-P5 can alleviate acne and act as an optimal FGFR2 inhibitor and reveal that YTHDF3 plays a crucial role in signalling between FGFR2 and AR." (PMID 36803994, 2023). "Our findings highlighted HA-P5 as an optimized FGFR2 inhibitor for acne treatment and uncovered a potential mechanism by which FGFR2 regulates AR signalling." (PMID 36803994, 2023). "Flutamide, a competitive antagonist of the AR, is most widely used and has been reported to have a favourable effect in women with PCOS as it decreases hirsutism and acne." (PMID 31466345, 2019). "Since AKR1C3 encodes an enzyme for the synthesis of androgen, the elevation of AKR1C3 enhances AR signalling, which is not conducive to treating acne." (PMID 36803994, 2023). "Moreover, our results show that HA-P5 inhibits both fibroblast growth factor receptor 2 (FGFR2) and androgen receptor (AR) signalling in SZ95 cells, reverses the acne-prone transcriptome, and decreases sebum secretion." (PMID 36803994, 2023). "Moreover, various mechanisms of insulin-like growth factor (IGF)-1 may aid the emergence of acne, such as through increased androgen stimulation and the disinhibition of the forkhead box (Fox)O1 transcription factor, leading to further activation of the androgen receptor (AR)." (PMID 34829964, 2021). "It is thus not surprising that isotretinoin reduces AR gene expression and transactivation as observed in isotretinoin-treated acne patients." (PMID 31080813, 2019).
pancreatic cancer (39 papers, 2002 to 2025). "The percentages of AR mutation-positive patients (AR+) for lung, stomach, ovarian, brain, and pancreas cancer were 48.28, 26.09, 20, 11.11, and 8.33, respectively." (PMID 35053623, 2022). "Activation of AR associated with human carcinogenesis in pancreatic cancer has been well described." (PMID 39556603, 2024). "However, to our knowledge, this is the first time that AR p.H875Y mutation has been reported for bladder, lung, stomach, ovarian, brain, and pancreas cancer." (PMID 35053623, 2022). "A role for non-genomic AR functions was observed with regard to motility and invasiveness of various AR-expressing cancer cell types (e.g., fibroblasts and PC-associated fibroblasts, fibrosarcoma, breast, prostate, colon and pancreas tumor cells) [29, 136 and unpublished data]." (PMID 26506594, 2016). "The cytokines interleukin-6 (IL-6) and interleukin-23 (IL-23) increase AR expression in prostate and pancreatic cancers." (PMID 40935826, 2025). "Another microRNA, miRNA-99b-5p, regulates through the mTOR/AR signaling pathway to trigger autophagy, and inhibit the proliferation of pancreatic cancer cells." (PMID 39056768, 2024). "Androgen receptor (AR), expressed in human normal pancreatic tissue and human pancreatic adenocarcinoma tissue, is another candidate for a therapeutic target for pancreatic cancer." (PMID 36834922, 2023). "Researchers have confirmed that interleukin-6 (IL-6) increased the activation of AR in pancreatic cancer cells by upregulating the phosphorylation of signal transducer and activator of transcription 3 (STAT3) and mitogen-activated protein kinase (MAPK)." (PMID 36834922, 2023). "Given the possible effects of androgens on pancreatic cancer, several prospective randomized controlled trials have explored the effects of androgen receptor inhibitors on pancreatic cancer; however, the findings have been inconsistent y." (PMID 36482455, 2022). "RAN promotes metastasis and invasion in pancreatic cancer by deregulating the expression of AR and CXCR4." (PMID 35626021, 2022). "As an example, KRAS activates GLI1 in pancreatic cancer cells, an androgen receptor (AR) protects GLI3 from proteolytic cleavage, and HH can be activated by the mTOR/S6K1 signaling." (PMID 30201866, 2018). "A number of in vitro/in vivo studies have tested the effects of antiandrogens and/or androgen deprivation in pancreatic cancer models, and have, for the most part, shown that inhibiting AR-signaling exerts anti-tumor effect." (PMID 28085048, 2017). "In sum, this set of experiments for the first time shows that EGF signaling relies on AR/Src complex in colon and pancreatic cancer cells." (PMID 24130806, 2013). "Androgen receptor has also been detected in cancerous tissues of pancreatic carcinoma, and it is thought that testosterone increases growth of this tumour." (PMID 12402154, 2002). "IL-6 also promoted the migration of pancreatic cancer cells in the presence of AR." (PMID 36834922, 2023). "Androgen receptor p.H875Y mutation (AR) was detected for the first time in bladder, lung, stomach, ovarian, brain, and pancreas cancer, all together in 51.3% of all cancer samples and in none of the healthy controls." (PMID 35053623, 2022). "Recent works have indicated the role of AR in the development of pancreatic cancer." (PMID 35163477, 2022). "Even so, the suggestion that androgen receptor blockade may significantly improve survival of pancreatic cancer patients warrants further testing." (PMID 12232752, 2002). "AR might also influence the progression of pancreatic cancer by affecting the circadian rhythm." (PMID 36834922, 2023). "Findings in this paper reveal that EGF transduces its signal through the AR/Src complex in HT1080 and various cancer-derived cell types, including colon and pancreatic cancer cells." (PMID 24130806, 2013).
pancreatic cancer (continued). "Although the incidence of AR expression is not well defined in pancreatic cancer, AR does appear to be expressed." (PMID 28085048, 2017). "In this review, we will outline the current evidence for testing AR-directed therapies in prostate, breast and other “non-hormonally” driven cancer like bladder, renal cell and pancreatic cancer, to name a few." (PMID 28085048, 2017).
glioma (38 papers, 2012 to 2026). A benign or malignant brain and spinal cord tumor that arises from glial cells (astrocytes, oligodendrocytes, ependymal cells). "In recent years, more attention has been given to understanding the pathogenic role of AR signaling in glioma biology." (PMID 41153666, 2025). "In our series, higher AR protein expression is associated with significantly poorer OS in glioma patients (p = 0.0022)." (PMID 41153666, 2025). "The results showed that nine genes were associated with the survival time of patients, among which BMP2 and AR were protective factors in glioma patients, and the other seven genes were risk factors." (PMID 39458959, 2024). "Consistent with previous findings showing that AR had pro-tumor properties in GBM tumor cells, we found in grade 3 gliomas that a low AR expression associated with better survival and one-carbon metabolism, especially in male IDHwt tumors." (PMID 36077653, 2022). "The gliomas type-specific mutated gene AR encodes the androgen receptor, whose role in the development of neural systems has been well established." (PMID 22691569, 2012). "Our prior research demonstrated that androgen receptor antagonists (ARAs) enhance survival in GBM mouse models by preferentially suppressing glioma stem cells." (PMID 41674836, 2026). "X-chromosome polysomy can play a role in the AR gene copy number and, consequently, in AR protein expression in glioma cells, controlling neoplastic transformation, especially in GBM IDH-wt." (PMID 41153666, 2025). "In analyzing the TCGA dataset of IDH wild-type glioma patients, we observed an inverse correlation between the expression of the three-miRNA signature and that of the AR." (PMID 40399259, 2025). "Bicalutamide, an androgen receptor antagonist, has been shown to be effective at inhibiting glioma progression both in vivo and in vitro." (PMID 40561176, 2025). "Currently, a variety of androgen antagonists are under investigation for their efficacy in AR-positive gliomas, particularly in IDH-wildtype GBMs." (PMID 41153666, 2025). "In IDH-mutant gliomas, AR immunoreactivity was more prevalent in astrocytomas than in 1p/19q codeleted oligodendrogliomas (p = 0.02)." (PMID 41153666, 2025). "Further research is required to explore and address the resistance mechanisms, the heterogeneity of gliomas, and the potential off-target effects of AR inhibitors." (PMID 41153666, 2025). "At present, there is no available data regarding the variations in copy number of the X chromosome and AR in gliomas." (PMID 41153666, 2025). "This aligns with data from previous research indicating that AR activation influences the proliferation of high-grade glioma cells and, primarily, of GBM cells." (PMID 41153666, 2025). "Since AR is reported to regulate glioma stem cell maintenance, we investigated the impact of the miRNA signature on the GBM cell staminal features and found a downregulation of several stem markers elicited by the signature." (PMID 40399259, 2025). "It is conceivable that in high-grade glioma, the neoplastic cells acquire additional copies of the X chromosome with consequent AR gene amplification and AR protein overexpression." (PMID 41153666, 2025). "As shown in Fig. 4Aleft panel, in silico analysis showed that the miRNA signature expression was significantly anticorrelated with AR expression in a TCGA dataset (IDH wild-type glioma patients, n = 94)." (PMID 40399259, 2025). "Immunohistochemically AR-positive gliomas showed a lower overall survival (OS) than AR-negative gliomas (p = 0.0022; HR = 3.1 (95%CI 1.45–6.6))." (PMID 41153666, 2025). "In our analysis, AR INTRA CAG-CGG repeats and AR CAG repeats were found to be hypermethylated in low-grade gliomas and hypomethylated in high-grade tumors." (PMID 41153666, 2025).
glioma (continued). "In this study, we aimed to investigate AR expression levels across gliomas of different histopathologic grades and molecular subtypes and to analyze the DNA methylation level of the AR and its co-regulators mapped on the X chromosome." (PMID 41153666, 2025). "The upregulation of circ-ASPH regulated AR expression in Glioma by targeting the miR-599/AR/SOCS2-AS1 signaling pathway, thus promoting glioma development." (PMID 39256355, 2024). "Silencing circ-ASPH can reduce the AR expression level to weaken proliferation, clonal formation, and the invasion of glioma cells." (PMID 39458959, 2024). "The known glioma risk variant rs55705857 in CCDC26 was co-inherited together with rare variants in GALNT13, MYO10 or AR in three out of six families carrying these rare variants, and it was also detected in affected cases in three additional families." (PMID 38773237, 2024). "It has been proven that SVIP is downregulated, but other ERAD components and androgen receptors (AR) are upregulated in glioma and androgen-dependent prostate cancer cell lines with R1881 treatment." (PMID 37408196, 2023). "The expression of mRNA and the presence of the AR protein in glioma and other brain tumors has been studied and reported for many years." (PMID 36361793, 2022). "For instance, upregulated circASPH contributed to glioma cell proliferation and aggressiveness by the miR-599/AR/SOCS2-AS1 signaling pathway." (PMID 35795047, 2022). "Confocal microscopy was performed to study the expression patterns of AR and glioma CSC marker genes on FFPE mouse brain tumor specimens." (PMID 34094902, 2021). "AR antagonists significantly suppress the expression of c-Myc, whose activity is required for proliferation, growth, and survival of glioma CSCs." (PMID 34094902, 2021). "We conclude that AR antagonists potently target glioma CSCs in addition to suppressing the overall proliferation of GBM cells as a mechanism supporting their repurposing for clinical applications treating GBM." (PMID 34094902, 2021). "In the present investigation, pharmacological inhibition of AR with AR antagonists in three glioma cell lines, as well as in two GICs, induced dose concentration-dependent death." (PMID 29731997, 2018). "Taken together, these results indicated that SVIP was downregulated by AR and also explained that its expression was low in high-grade glioma tissue samples." (PMID 28423563, 2017). "In summary, we have found that androgens function to promote glioma cell proliferation through activating AR signaling." (PMID 28423563, 2017). "The incidence of glioma in men is higher than that in women; however, little is known about the expression and basic function of the androgen receptor (AR) in gliomas." (PMID 28423563, 2017). "All these results illustrated that the decreased SVIP expression, as well as increased AR expression, in glioma tissues correlated with gliomas progressing from low to high grades." (PMID 28423563, 2017). "Hence, the AR expression may be associated with glioma's tumorigenesis in the brain." (PMID 28423563, 2017). "Consistent with the Western blot result, the immunohistochemistry staining showed lower expression of SVIP in high-grade gliomas than in the NC, and a reverse trend of AR expression in the nucleus was observed." (PMID 28423563, 2017). "Nonetheless, GR signaling may also contribute to the overall effect of MF, so future studies to examine the relative contributions of PR, GR and AR pathways in glioma cells are guaranteed." (PMID 41439468, 2026). "Moreover, immunohistochemical analysis for the detection of AR positivity is an inexpensive and simple investigation, which can be easily performed in glioma patients." (PMID 41153666, 2025). "DHX15, though reported to act as a tumor suppressor in some cancers, may contribute to glioma progression via androgen receptor signaling and warrants further study." (PMID 40561176, 2025).